SLC4A11 (solute carrier family 4 member 11)
Description:
Multifunctional transporter with an impact in cell morphology and differentiation. In the presence of borate B(OH)4(-), acts as a voltage-dependent electrogenic Na(+)-coupled B(OH)4(-) cotransporter controlling boron homeostasis. At early stages of stem cell differentiation, participates in synergy with ITGA5-ITGB1 and ITGAV-ITGB3 integrins and BMPR1A to promote cell adhesion and contractility that drives differentiation toward osteogenic commitment while inhibiting adipogenesis (By similarity). In the absence of B(OH)4(-), acts as a Na(+)-coupled OH(-) or H(+) permeable channel with implications in cellular redox balance. Regulates the oxidative stress response in corneal endothelium by enhancing antioxidant defenses and protecting cells from reactive oxygen species. In response to hypo-osmotic challenge, also acts as a water permeable channel at the basolateral cell membrane of corneal endothelial cells and facilitates transendothelial fluid reabsorption in the aqueous humor. In the presence of ammonia, acts as an electrogenic NH3/H(+) cotransporter and may play a role in ammonia transport and reabsorption in renal Henle's loop epithelium.
Synonyms: NaBC1; BTR1; dJ794I6.2; FECD4; CDPD1; CHED; CHED2
Tractability: Small molecule: a structure with a bound ligand is known. Antibody: UniProt places it where antibodies can reach, with high confidence; UniProt predicts a signal peptide or a membrane-spanning region; its Gene Ontology location is reachable by antibodies, with medium confidence. PROTAC: ubiquitination databases record sites on it.
Gene: Protein-coding gene on chromosome 20 (3,227,417 to 3,239,580, reverse strand). Ensembl gene ENSG00000088836.
Subcellular location: Cell membrane; Basolateral cell membrane
Subcellular location (Human Protein Atlas): Nucleoplasm; Vesicles
Gene Ontology:
Molecular function: bicarbonate transmembrane transporter activity; borate efflux transmembrane transporter activity; protein dimerization activity; proton channel activity; proton transmembrane transporter activity; sodium channel activity; water transmembrane transporter activity; solute:inorganic anion antiporter activity
Biological process: bicarbonate transport; borate transport; cellular hypotonic response; cellular response to oxidative stress; intracellular monoatomic cation homeostasis; proton transmembrane transport; regulation of mitochondrial membrane potential; sodium ion transport; fluid transport; monoatomic ion homeostasis; regulation of mesenchymal stem cell differentiation; borate transmembrane transport; monoatomic anion transport; sodium ion transmembrane transport; water transport
Cellular component: apical plasma membrane; basolateral plasma membrane; plasma membrane; vesicle membrane; membrane
Genetic constraint (gnomAD): Loss-of-function variants: 74 observed, 100.13 expected, observed/expected ratio (o/e) 0.74, 90% interval 0.61 to 0.9. The upper end of that interval is the gene's LOEUF score, 0.9, which puts it in group 3 of 6, group 1 being the genes least tolerant of losing a copy. Missense variants: 1,081 observed, 1,236.4 expected, observed/expected ratio (o/e) 0.87, 90% interval 0.83 to 0.92. Synonymous variants: 548 observed, 541 expected, observed/expected ratio (o/e) 1.01, 90% interval 0.94 to 1.09.
Homologues: Orthologues: chimpanzee SLC4A11 (98% identical), macaque SLC4A11 (96% identical), rabbit SLC4A11 (88% identical), rat Slc4a11 (84% identical), mouse Slc4a11 (84% identical), guinea pig SLC4A11 (82% identical), dog SLC4A11 (82% identical), pig SLC4A11 (82% identical), tropical clawed frog slc4a11 (71% identical), zebrafish slc4a11 (58% identical), Caenorhabditis elegans abts-2 (31% identical). Paralogues in human: SLC4A4 (26% identical), SLC4A7 (26% identical), SLC4A8 (25% identical), SLC4A10 (25% identical), SLC4A3 (25% identical), SLC4A2 (24% identical), SLC4A5 (24% identical), SLC4A9 (24% identical), SLC4A1 (23% identical).
Diseases named in the same sentence as SLC4A11 in open-access papers:
SLC4A11 is named in the same sentence as 54 diseases in open-access papers, as found by Europe PMC text mining. Sharing a sentence is not in itself a finding about the gene and the disease. The quoted sentences say what the papers report.
Fuchs endothelial corneal dystrophy (27 papers, 2008 to 2026). Fuchs endothelial corneal dystrophy (FECD) is the most frequent form of posterior corneal dystrophy (see this term) and is characterized by excrescences on a thickened Descemet membrane (corneal guttae), generalized corneal edema, with gradually decreased visual acuity. "Rare SLC4A11 variants have also been linked to Fuchs corneal endothelial dystrophy (FECD), though the evidence for a causal role in FECD remains insufficient." (PMID 40563515, 2025). "SLC4A11 mutations can lead to corneal endothelial dystrophy and hearing deficits that are recapitulated in SLC4A11 knock-out mice." (PMID 35053313, 2022). "SLC4A11 mutations cause congenital hereditary endothelial dystrophy and some cases of Fuchs endothelial corneal dystrophy." (PMID 34686736, 2021). "A hallmark of corneal endothelial dystrophies and the Slc4a11 KO CHED model is increased oxidative stress within corneal endothelium." (PMID 34190974, 2021). "Three genetic corneal dystrophies [congenital hereditary endothelial dystrophy type 2 (CHED2), Harboyan syndrome and Fuchs endothelial corneal dystrophy] arise from mutations of the SLC4a11 gene, which cause blindness from fluid accumulation in the corneal stroma." (PMID 23813972, 2013). "Two blinding corneal dystrophies, pediatric-onset congenital hereditary endothelial dystrophy (CHED) and some cases of late-onset Fuchs endothelial corneal dystrophy (FECD), are caused by SLC4A11 mutations." (PMID 31273259, 2019). "More significantly, SLC4A11 causes some cases of Fuchs endothelial corneal dystrophy (FECD, OMIM #613268), the most common cause of corneal transplant, accounting for up to 25% of corneal grafts." (PMID 23813972, 2013). "Heterozygous SLC4A11 mutations have recently been reported in Fuchs endothelial corneal dystrophy (FECD), a late-onset progressive disorder of the corneal endothelium, indicating that carriers parents of affected CHED2 or Harboyan children might be at risk of developing late-onset corneal dystrophy." (PMID 18922146, 2008). "Fuchs' endothelial corneal dystrophy (FECD) and congenital hereditary endothelial dystrophy (CHED) are corneal endothelial pathologies associated with SLC4A11 gene variants." (PMID 42115719, 2026). "Mutations in SLC4A11 have been found in patients with congenital hereditary endothelial dystrophy type 2 (CHED2) and have also been linked to Fuchs endothelial corneal dystrophy (FECD) and KC." (PMID 41153364, 2025). "Several SLC4A11 homozygous or compound heterozygous mutations are associated with congenital hereditary endothelial dystrophy (CHED), a rare corneal endothelial dystrophy that can manifest in infancy." (PMID 35053313, 2022). "The Solute Carrier Family 4 Member 11 protein (SLC4A11; OMIM 610206) encodes the membrane transport protein of the basolateral corneal endothelium, causing CHED and Fuchs endothelial corneal dystrophy (FECD)." (PMID 33816482, 2021). "In this review, we first summarized the mutations of COL8A2, TCF4, TCF8, SLC4A11 and AGBL1 genes in Fuchs endothelial corneal dystrophy." (PMID 34130750, 2021). "Mutations in SLC4A11, a Na+ dependent OH− transporter, cause congenital hereditary endothelial dystrophy (CHED) and Fuchs’ endothelial corneal dystrophy (FECD), the two most common forms of endothelial degeneration." (PMID 28642546, 2017). "In humans, mutations in SLC4A11 are associated with congenital hereditary endothelial dystrophy (CHED), corneal dystrophy and perceptive deafness (Harboyan syndrome) and late onset Fuchs endothelial corneal dystrophy (FECD)." (PMID 24155723, 2013). "Heterozygous changes in SLC4A11 have been reported in cases of late onset Fuchs endothelial corneal dystrophy (FECD; OMIM 136800) in which haploinsufficiency and accumulation of aberrantly folded protein is reported to result in FECD pathology." (PMID 21203343, 2010).
Fuchs endothelial corneal dystrophy (continued). "The role of SLC4A11 in oxidative stress and mitochondrial dysfunction has been of increasing interest to several research groups because of its potential contribution to the pathogenesis of corneal endothelial dystrophies." (PMID 40563515, 2025). "It has been reported that three mutants, located in the EL3, p.Val507Ile, p.Val575Met, and p.Tyr526Cys, are associated with the development of Fuchs endothelial corneal dystrophy (FECD), which may be caused by mutations in this region disrupting the structure of SLC4A11." (PMID 37894847, 2023). "Mutations in SLC4A11 are considered responsible for human corneal disorders, such as autosomal recessive congenital hereditary endothelial dystrophy (CHED2), Harboyan syndrome and Fuchs endothelial corneal dystrophy." (PMID 31833218, 2019). "In conclusion, our data suggests a possible role of SLC4A11 in regulating oxidative stress, and might be responsible for both the etiology and treatment of corneal endothelial dystrophy." (PMID 28642546, 2017). "Our data provide an explanation for the role of SLC4A11 in endothelial corneal dystrophies." (PMID 23813972, 2013). "Moreover, SLC4A11 was identified to be responsible for three corneal endothelial dystrophies, recessive congenital hereditary endothelial dystrophy (CHED2), late onset Fuchs endothelial dystrophy (FECD), and corneal dystrophy with perceptive deafness (Harboyan syndrome)." (PMID 23734078, 2013). "Mutations in SLC4A11 disrupt endothelial fluid transport, leading to dystrophies like congenital hereditary endothelial dystrophy (CHED) and Fuchs endothelial corneal dystrophy (FECD), but the precise pathogenic mechanisms are unresolved." (PMID 41210874, 2025). "Furthermore, Slc4a11−/− MCECs recapitulate the glutaminolysis defects observed in Slc4a11−/− mouse corneal endothelium, providing an excellent tool to study the pathogenesis of SLC4A11 mutations associated with corneal endothelial dystrophies and to screen potential therapeutic agents." (PMID 28738416, 2017).
corneal dystrophies (15 papers, 2009 to 2024). "The genotype of this proband includes a missense variant p.(Gly769Arg) in heterozygosis in the SLC4A11 gene, described in GnomAD to be associated with corneal dystrophy." (PMID 37895187, 2023). "Congenital hereditary endothelial dystrophy (CHED) is a rare form of corneal dystrophy caused by SLC4A11 gene variations." (PMID 36115991, 2022). "Studies of recombinant SLC4A11 are ongoing, working to understand SLC4A11 function and ultimately to ameliorate corneal dystrophy symptoms associated with defective SLC4A11." (PMID 31273259, 2019). "SLC4A11 mutations have also been associated with the autosomal recessive form of another corneal dystrophy, congenital hereditary endothelial dystrophy (CHED)." (PMID 28384203, 2017). "Taken together, these results suggest that SLC4A11 appears to be a Vps35/retromer cargo, and Vps35-regulation of SLC4A11 trafficking may underlie Vps35/retromer regulation of corneal dystrophy." (PMID 28934248, 2017). "If loss of SLC4A11-mediated water-flux causes corneal dystrophies, then loss of AQP1 might cause the same phenotype as loss of SLC4A11." (PMID 23813972, 2013). "In this model, corneal endothelial Vps35 is necessary for SLC4A11’s endosome-to-Golgi trafficking, and thus promoting SLC4A11’s cell surface targeting and protein stability, which may underlie Vps35’s involvement in the pathogenesis of corneal dystrophy." (PMID 28934248, 2017). "Apart from CHED, a mutation in SLC4A11 also causes a form of autosomal dominant Fuch’s corneal endothelial dystrophy (FECD) and Harboyan syndrome or corneal dystrophy-perceptive deafness." (PMID 36115991, 2022). "If SLC4A11 is required to prevent corneal dystrophy through NH3/H+/OH- transport, then compensation by altered expression of ion transporters would be expected." (PMID 34686736, 2021). "To better understand the role of SLC4A11 protein in corneal dystrophies, we took advantage of a previously characterized slc4a11−/− mice to perform a transcriptome analysis of adult mouse cornea." (PMID 34686736, 2021). "Intriguingly, cell surface targeting of SLC4A11, a membrane transport protein (OH- /H+ /NH3 /H2O) of corneal endothelium, whose mutations have been identified in patients with corneal dystrophy, was impaired in Vps35-deficient cells and cornea." (PMID 28934248, 2017). "Ion transporters allow the endothelial cells to function as a barrier between the aqueous humor of the anterior chamber and the dehydrated corneal stroma, so the causal role of pathogenic variants in SLC4A11 in corneal dystrophies is not surprising." (PMID 37441688, 2023). "To date, most of the work on SLC4A11 is concentrated on corneal dystrophies." (PMID 35163645, 2022). "The corneal fluid accumulation central to corneal dystrophies led us to consider whether the human protein, SLC4A11, functions as a previously unrecognized water movement pathway." (PMID 23813972, 2013). "Corneal dystrophies associated with recessive pattern of inheritance include, Corneal hereditary endothelial dystrophy 2 (CHED2), Corneal Dystrophy Gelatinous Drop-Like (CDGDL), and Corneal Dystrophy Macular with mutations in SLC4A11, M1S1, and CHST6, respectively." (PMID 32823625, 2020). "However, it remains to be determined if Vps35 mutation or deficiency occurs in corneal dystrophy patients, and if expression of SLC4A11 could attenuate corneal dystrophy in Vps35 mutant mice." (PMID 28934248, 2017). "Therefore, the purpose of this study was to characterize the expression levels of the entire Slc4 family of genes relative to those of Slc4a4 and Slc4a11 in the mouse corneal endothelium to identify further SLC4 members that can serve as candidate genes for analysis in corneal dystrophies." (PMID 23734078, 2013).
corneal dystrophies (continued). "Given the known involvement of SLC4A4 and SLC4A11 in corneal dystrophies, we speculate that the other two highly expressed genes in the uncultured corneal endothelium, SLC4A2 and SLC4A7, are worthy of being considered as potential candidate genes for corneal endothelial diseases." (PMID 23734078, 2013). "In addition to the unbiased analysis of genes with altered expression in slc4a11−/− mouse cornea (GO and KEGG analysis above), we also considered the significance of gene alterations in the context of corneal dystrophy biology." (PMID 34686736, 2021).
corneal edema (12 papers, 2013 to 2026). "The mutations in SLC4A11, which relate to diseases of the corneal endothelium, manifest progressive corneal edema and opacification with a bluish-gray ground glass appearance and the incrassation of the cornea." (PMID 39669368, 2024). "SLC4A11 mutations cause dysfunction of endothelial cells leading to thickening of the DM and corneal edema." (PMID 28642546, 2017). "We hypothesized that a trigger for these changes in protein expression and subsequent corneal edema was the oxidative stress caused by Slc4a11 deletion." (PMID 37296649, 2023). "In these models, the decrease in corneal endothelial cell density in SLC4A11 KO mice was either insignificant or developed later compared to the corneal edema." (PMID 40563515, 2025). "Pathogenic variants in SLC4A11 are the most commonly identified genetic cause of congenital hereditary endothelial dystrophy (CHED), which presents with early onset corneal edema and, rarely, concomitant congenital glaucoma." (PMID 41011222, 2025). "In various models, the SLC4A11 KO mice exhibited significant corneal edema, which appears to be influenced by impaired lactate efflux from the corneal stroma." (PMID 40563515, 2025). "The finding that Slc4a11 knockout mice have approximately the same CEnC density as wild type mice at 10 weeks of age, but exhibit a significantly lower CEnC density by 40 weeks of age, suggests that decreased CEnC viability may be the cause of the congenital corneal edema in individuals with CHED." (PMID 38252645, 2024). "The expression of SLC4A11 in the corneal endothelium and inner ear patterns the deficits seen in CHED with corneal edema and hearing loss (Harboyan syndrome)." (PMID 26451371, 2015). "Consistent with these microscopic changes, slc4a11−/− mice exhibit macroscopic corneal oedema and a progressive increase in corneal thickness." (PMID 23813972, 2013). "Adult slc4a11−/− mice exhibited macroscopic corneal edema, a progressive increase in corneal thickness, profound disorganization of the corneal endothelium, and CEC swelling, recapitulating key aspects of the progression of human SLC4A11-associated diseases." (PMID 34686736, 2021). "Moreover, systemic delivery of MitoQ could slow down the progression of corneal edema in young SLC4A11 KO mice, which is similar to the reductions in corneal edema seen when glutamine catabolism was circumvented with dimethyl αketoglutarate eye drops." (PMID 35053313, 2022). "Possibly, the primary consequence of SLC4A11 dysfunction is corneal edema, but not oxidative-stress-mediated cell death." (PMID 40563515, 2025). "Perhaps the primary result of SLC4A11 dysfunction is corneal edema, but not oxidative-stress-mediated cell death." (PMID 40563515, 2025).
corneal endothelial dystrophies (12 papers, 2010 to 2026). "Functional analyses of mutations associated with endothelial dystrophies have shown that many lead to reduced levels of SLC4A11 protein or its mature, glycosylated form." (PMID 40563515, 2025). "CHED and FECD are two major forms of corneal endothelial dystrophies that lead to progressive opacity of the cornea and gradual vision loss and are associated with mutations in SLC4A11 gene." (PMID 28642546, 2017). "Therefore, the KO phenotype recapitulates CHED and indicates that the loss of SLC4A11 function is sufficient to cause endothelial dystrophy." (PMID 35053313, 2022). "Considering this variability in expression, all cases of endothelial dystrophies should be screened for the presence of SLC4A11 and/or ZEB1 changes for confirmation and categorization." (PMID 21203343, 2010).
autosomal recessive CHED (6 papers, 2008 to 2025). "In 2006, mutations in the SLC4A11 gene within this region were identified as the cause of autosomal recessive CHED." (PMID 40563515, 2025). "In family GEL-007, the proband and her sister were found to harbour a likely pathogenic homozygous missense variant in SLC4A11 (c.1343G>A p.(Gly448Asp)), a gene known to be associated with autosomal recessive congenital hereditary endothelial dystrophy (CHED)." (PMID 38755526, 2024). "The interest in this K+-dependent Na+/Ca2+ exchangers is related to the recent association of another solute carrier (SLC4A11) with autosomal recessive CHED." (PMID 18253095, 2008). "The SLC4A11 gene, which codes for sodium bicarbonate transporter-like protein 11, has been previously associated with autosomal recessive congenital hereditary endothelial dystrophy (CHED2) which is also classified as a primary defect of the corneal endothelium." (PMID 22737377, 2010). "The molecular expression pattern of SLC4A11 correlates with the observed clinical phenotype for autosomal recessive CHED." (PMID 26451371, 2015). "The SLC4A11 gene (MIM: 610206), associated with autosomal recessive congenital hereditary endothelial dystrophy (CHED; MIM: 217700), was detected in the multiplex family GEL-007, two affected individuals had a homozygous missense variant (c.1343G>A p.(Gly448Asp))." (PMID 38755526, 2024).